IRS2 (insulin receptor substrate 2)
Diseases named in the same sentence as IRS2 in open-access papers (continued):
Sharing a sentence is not in itself a finding about the gene and the disease.
Alzheimer disease (6 papers, 2009 to 2025). A progressive, neurodegenerative disease characterized by loss of function and death of nerve cells in several areas of the brain leading to loss of cognitive function such as memory and language. "Accumulating studies have demonstrated that a reduction in intracellular signaling mediated by IGF-1 receptor/IRS2 exerts neuroprotective effects in Alzheimer’s disease." (PMID 38674428, 2024). "As impaired insulin signalling (IIS) is a risk factor for Alzheimer’s disease we crossed mice (Tg2576) over-expressing human amyloid precursor protein (APP), with insulin receptor substrate 2 null (Irs2−/−) mice which develop insulin resistance." (PMID 19523444, 2009). "However, by contrast, both IRS-1 and IRS-2 expressions decrease in neurons of humans with Alzheimer’s disease and both insulin and IGF-1 signaling are patently disturbed in brains affected by Alzheimer’s disease." (PMID 25755673, 2015).
endometrial cancer (6 papers, 2014 to 2024). Primary or metastatic malignant neoplasm involving the endometrium (mucous membrane that lines the endometrial cavity). "Several case-control studies found significant associations between IRS2 rs1805097 polymorphism and gastric, colon and endometrial cancer." (PMID 24497996, 2014).
breast tumor (5 papers, 2016 to 2024). "Both IRS1 and IRS2 are expressed in breast tumors, but their expression patterns and functions differ in a subtype-dependent manner." (PMID 39305958, 2024). "The absence of IRS2 nuclear localization was also observed in FFPE sections of human breast tumors and biochemical extraction of cells." (PMID 39305958, 2024). "Multiple IRS-1 and IRS-2 clones [IRS-1 (#10 and #20) and IRS-2 (#1 and #6)] were included in these and all subsequent analyses as a means to circumvent both clonal and temporal bias and more accurately depict the role of IRS adaptor proteins in breast tumor biology." (PMID 26991655, 2016). "IRS-2 is highly expressed in invasive breast tumors, whereas IRS-1 is predominantly expressed in localized tumors, and rescue of IRS-2, but not IRS-1, expression in IRS1/2 double null breast tumor cells restores invasive potential." (PMID 36556357, 2022).
diabetic nephropathy (5 papers, 2015 to 2020). "IRS2 expression is preserved in the renal cortex of insulin-resistant patients or even enhanced in tubules of patients with diabetic nephropathy." (PMID 32377524, 2020). "IRS2 is also overexpressed in kidney tubular epithelial cells in biopsies from humans with diabetic nephropathy." (PMID 27514532, 2016). "The impairment of IRS2 signaling in the podocyte in the onset of diabetic nephropathy has been very recently suggested; Santamaria and colleagues demonstrated that phosphatase and tensin homolog (PTEN) and IRS2 were essential for insulin signaling in podocytes." (PMID 27247938, 2016). "However, treatment of db/db mice with bioactive peptides nephrilin or anephril significantly reduced IRS2, p-IRS1-Ser307, serum/glucocorticoid-regulated kinase 1 and phospho-PKC-α/β which, when elevated, are associated with diabetic nephropathy." (PMID 27514532, 2016).
liver cancer (5 papers, 2019 to 2023). An epithelial or non-epithelial malignant neoplasm that arises from the liver. "TAZ has previously been shown to regulate IRS2 expression in liver cancer and to alter insulin sensitivity, but we did not observe effects of TAZ on IRS1/2 expression or insulin sensitivity in mice." (PMID 34622775, 2021). "In addition, Hippo signaling interacts with AKT signaling by regulating IRS2 expression to prevent liver cancer progression." (PMID 36975518, 2023).
amyloid (4 papers, 2015 to 2025). "Several reports have indicated that IRS-2 participates in reducing amyloid deposition and cognitive deficits in a transgenic mouse model of AD." (PMID 25978724, 2015). "These behavioural improvements are likely underpinned by the observed reduction in amyloid plaque burden and normalisation of key molecular markers, including increased Bdnf expression, upregulation of the mitochondrial regulator Irs2, and modulation of insulin receptor-related pathways." (PMID 40862772, 2025).
coronary artery disease (4 papers, 2012 to 2025). "Naturally occurring polymorphisms in PI3K, Akt, and IRS2 affect risk for coronary artery disease, metastatic lung cancer, and survival in esophagal cancer." (PMID 25774510, 2015).
female infertility (4 papers, 2013 to 2023). Diminished or absent ability of a female to achieve conception. "Mutation of Irs-2 in mice also causes female sterility with other major defects." (PMID 31009498, 2019). "The deletion of insulin receptor substrate-2, a component of the insulin/IGF-1 signalling cascade, causes female infertility through, i.a., disturbances in pituitary functions, leading to reduced numbers of gonadotrophs and decreased LH concentration." (PMID 37880346, 2023). "Global deletion of IRS-2 (IRS-2−/−) in mice cause metabolic dysfunction and female infertility." (PMID 22851226, 2013).
Hepatic fibrosis (4 papers, 2019 to 2020). The presence of excessive fibrous connective tissue in the liver. "Altogether, results in the BDL model suggest that IRS2 deficiency retards the progression of cholestasis-induced liver fibrosis, an effect that is likely due to a slow-down of HSC activation." (PMID 31262748, 2019). "In order to investigate the impact of Irs2 knockdown in liver fibrosis, cholestatic liver injury was induced by BDL in WT and IRS2KO female mice." (PMID 31262748, 2019). "Histological analysis performed at 3 and 7 days post-BDL showed that the absence of IRS2 reduced the degree of hepatic fibrosis." (PMID 31262748, 2019). "Our discovery that IRS2 silencing in HSCs also promoted fibrogenesis while limiting hepatocyte differentiation and FGFR2-IIIb expression in coculture recapitulated the increase in liver fibrosis and reduced Fgf7/Fgfr2-IIIb expression described in Irs2−/− mice during DDC treatment." (PMID 30695023, 2019).
invasive breast carcinoma (4 papers, 2017 to 2023). A carcinoma that infiltrates the breast parenchyma. "IRS-2 staining was not present in the nuclei of any ADC tumors, similar to our previous observations in invasive breast cancer." (PMID 31393907, 2019).
myeloproliferative neoplasm (4 papers, 2016 to 2022). A clonal hematopoietic stem cell disorder, characterized by proliferation in the bone marrow of one or more of the myeloid (i.e., granulocytic, erythroid, megakaryocytic, and mast cell) lineages. "Considering the previous findings in nonhematologic tissues, our research group identified a constitutive protein association between IRS2 and JAK2 in myeloproliferative neoplasm (MPN) models, which present constitutive JAK2 activation due to a V617F mutation." (PMID 30328953, 2018). "Recent data indicate that IGF1R/IRS signaling is a potential therapeutic target in BCR-ABL1-negative myeloproliferative neoplasms (MPN); in this pathway, IRS2 is involved in the malignant transformation induced by JAK2V617F, and upregulation of IGF1R signaling induces the MPN phenotype." (PMID 32296029, 2020).
asthma (3 papers, 2020 to 2025). "IL-4 binding to macrophage receptors via insulin receptor substrate 2 (IRS-2) signaling induces M2 macrophage differentiation, associated with severe asthma." (PMID 40893770, 2025).
Cognitive impairment (3 papers, 2015 to 2024). Abnormal cognition is characterized by deficits in thinking, reasoning, or remembering. "Follow-up studies are needed to investigate the mechanism by which the sequence differences in IRS2 cause cognitive impairment and whether the differences can be used as a therapeutic target in patients with SAH." (PMID 39061961, 2024).
Infertility (3 papers, 2021 to 2022). "IGF1 signaling in the ovary was initially thought to be mediated by insulin receptor substrate 2 (IRS2), as the deletion of the Irs2 gene caused infertility." (PMID 33808081, 2021). "They showed that FSH could increase theexpression of the IRS-2 gene and the functional deficiency of FSH reducedfollicular growth and metabolism and led to infertility." (PMID 36273315, 2022). "They further found that after IRS-2 knockdown by siRNA, the defect of FSH may cause the deceleration of follicular growth, which can lead to infertility." (PMID 33446212, 2021).
myocardial infarction (3 papers, 2019 to 2025). Gross necrosis of the myocardium, as a result of interruption of the blood supply to the area, as in coronary thrombosis. "In another study, knocking out the cardiac-specific PHD1 gene provides cardioprotection after myocardial infarction by activating key molecules, such as Insulin Receptor Substrate 2 (IRS2) and Heat Shock Protein Family A (Member 12B) (HSPA12B), involved in survival and angiogenesis." (PMID 41296459, 2025).
polycystic ovary syndrome (3 papers, 2014 to 2025). A disorder that manifests as multiple cysts on the ovaries. "Additionally, given the recognized antiapoptotic role of IRS-2, its increased presence in small antral follicles could indicate a potential association with cyst accumulation in polycystic ovaries." (PMID 38540265, 2024). "The GlyAsp1057 polymorphism, which is common in IRS2, appears to affect susceptibility to T2DM in both African American and white women with polycystic ovary syndrome, as evidenced by higher glucose concentrations at the 2-hour point in the oral glucose tolerance test." (PMID 40747301, 2025).
thyroid cancer (3 papers, 2017 to 2022). "Moreover, since insulin receptor substrate 2 (IRS2), a known oncogene, was confirmed to be a direct target of miR-141, its overexpression blocks cell proliferation and induces cell apoptosis of thyroid cancer." (PMID 36158660, 2022).
allergic disease (2 papers, 2015 to 2018). An immune response that occurs following re-exposure to an innocuous antigen, and that requires the presence of existing antibodies against that antigen. "Substantial progress has been made over the past 28 years in understanding the contribution of 4PS (IRS1 or IRS2) to IL-4- and IL-13-stimulated responses in the context of allergic diseases, however, as noted throughout, there is still much work to be done." (PMID 29868002, 2018). "However, our current understanding of the relative roles of IRS1 and IRS2 in mediating and modulating allergic diseases is quite limited." (PMID 29868002, 2018).
chronic myelogenous leukemia (2 papers, 2022 to 2024). "Activating mutations of the IRS-2 have been implicated in the pathogenesis of chronic myeloid leukemia refractory to tyrosine kinase inhibitor treatment." (PMID 38159164, 2024).
COVID-19 (2 papers, 2022 to 2023). A disease caused by infection with severe acute respiratory syndrome coronavirus 2. "In summary, the expression patterns of CD36, GLUT2, IRS1, IRS2, PDX1, and PPARG in the pancreas were altered upon SARS-CoV-2 infection, implying that islet function may be compromised in patients with COVID-19." (PMID 35343389, 2022). "In the COVID-19 patient without SARS-CoV-2 virus expression in the pancreas (SARS-CoV-2 negative), CD36, GLUT2, IRS2, and PDX1 were widely distributed in the pancreatic, serous acini, duct (exocrine gland) and islet (endocrine gland)." (PMID 35343389, 2022).
hepatic (2 papers, 2022 to 2023). "Exenatide may improve adipose tissue-associated hepatic IR by inhibiting adipokines and regulating the expression of key proteins in the IRS2/PI3K/Akt2 pathway." (PMID 36246878, 2022). "After inhibiting miR-34a in a high-fat-induced hepatic IR model, the expression of p-IRS2 (Ser1100) was significantly downregulated, while its downstream p-Akt (Ser473) expression was significantly increased, leading to impaired glucose metabolism-related indices." (PMID 37960269, 2023).
Impaired glucose tolerance (2 papers, 2020 to 2022). An abnormal resistance to glucose, i.e., a reduction in the ability to maintain glucose levels in the blood stream within normal limits following oral or intravenous administration of glucose. "Despite the clear signs of impaired glucose tolerance found in both, the GTT and the ITT, expression of insulin receptor (Ir) and insulin receptor substrate 2 (Irs2) mRNA was similar between both groups in muscle and liver tissue." (PMID 32881925, 2020).
intrahepatic cholangiocarcinoma (2 papers, 2015 to 2025). A carcinoma that arises from the intrahepatic bile duct epithelium in any site of the intrahepatic biliary tree. "We examined two iCCA cell lines and 86 cases of intrahepatic cholangiocarcinoma to analyze copy number of three target genes, including cullin 4A (CUL4A), insulin receptor substrate 2 (IRS2), and transcription factor Dp-1 (TFDP1) at 13q34 by quantitative real-time polymerase chain reaction." (PMID 26684807, 2015).
kidney damage (2 papers, 2010 to 2018). "No significant histological changes were seen in Irs2-/- kidneys compared to wild-type at any age group, using a range of specific stains for markers of kidney damage." (PMID 20604929, 2010).
leiomyosarcoma (2 papers, 2002 to 2018). An uncommon, aggressive malignant smooth muscle neoplasm, usually occurring in post-menopausal women. "Discussion: Our findings tend to exclude that the malignancy displayed by uterine leiomyosarcomas might be directly linkedto the activation of distinct IRS-1- or IRS-2-dependent pathways." (PMID 18521338, 2002).
liver disease (2 papers, 2017 to 2019). "Conversely, the expression of the down-regulated genes, including many metabolism- (e.g., leptin receptor and insulin receptor substrate 2) and mitochondria-related genes, decreased with the progression of liver disease, and BCAA supplementation rescued this down-regulation." (PMID 28212548, 2017).
lymph node metastasis (2 papers, 2021). "However, the high expression level of ATG12 but not IRS2 was correlated with OS in terms of key patient symptoms such as clinicopathological characteristics, the presence of lymph node metastasis, and degree of tumor differentiation, or whether the patient had distant metastasis." (PMID 34976838, 2021).
myelodysplastic syndrome (2 papers, 2018 to 2023). A clonal hematopoietic disorder characterized by dysplasia and ineffective hematopoiesis in one or more of the hematopoietic cell lines. "The degree of IRS2 deficiency was inversely correlated with the reduction in hematopoietic cells in patients with myelodysplastic syndrome, demonstrating the importance of an IRS2 level that is within the normal range for healthy hematopoiesis." (PMID 37325570, 2023).
nonalcoholic fatty liver (2 papers, 2021 to 2023). "Apart from the progressive hyperglycemic environment, dietary fat promotes IRS‐2 phosphorylation in the nonalcoholic fatty liver." (PMID 36721851, 2023).
osteoporosis (2 papers, 2022 to 2024). A condition of reduced bone mass, with decreased cortical thickness and a decrease in the number and size of the trabeculae of cancellous bone (but normal chemical composition), resulting in increased fracture incidence. "In another study, miR‐7b‐5p was found to inhibit the adipogenic differentiation of human BMSCs via insulin receptor substrate 2 (IRS2) targeting, thus alleviating the development of osteoporosis." (PMID 38748896, 2024).
pancreatic cancer (2 papers, 2015 to 2021). "This receptor and its adaptor proteins IRS-1 and IRS-2 are expressed in pancreatic cancer cell lines as well as in human PDA." (PMID 25885700, 2015). "IRS-2 was found to overexpress in human pancreatic cancer and might stimulate tumor growth through enhancing mitogenic signaling via the PI3-kinase pathway." (PMID 33804263, 2021).
Polydipsia (2 papers, 2013 to 2018). Excessive thirst manifested by excessive fluid intake. "Noteworthy, IRS2-KO mice did not display polydipsia at this stage yet; therefore, both control and IRS2-KO mice ingested almost the same amount of water and consumed almost the same amount of NaW, which was approximately 120 mg per kg body weight per day." (PMID 30003110, 2018).
preeclampsia (2 papers, 2011 to 2016). Preeclampsia is a hypertensive disorder of pregnancy that is characterized by new-onset hypertension with proteinuria presenting after 20 weeks of gestation, and depending on mild or severe forms may initially present with severe headache, visual disturbances, and hyperreflexia. "This may be explained by IRS-1 and IRS-2 inhibition due to serine-phosphorylation and subsequent impairment of downstream insulin signaling in preeclampsia." (PMID 27738431, 2016).
prostate tumor (2 papers, 2011 to 2024). "For example, 13 novel interactors of MPeM-associated genes were associated with prostatic neoplasms (MPeM genes are shown in bold): MET-SLC26A4, DPYD-SULT2A1, CTNNB1-LAMB2, IRS2-MPO, HRAS-ZFP36L2, VEGFB-UCP3, PRDM1-HPGD, NSD1-NPR3, KEAP1-SLC5A5, MET-FOXA3, RHEB-NOS3, HRAS-HBG1 and JAK1-CBR1." (PMID 39516360, 2024).
schizophrenia (2 papers, 2015 to 2022). A major psychotic disorder characterized by abnormalities in the perception or expression of reality. "A similar synonymous codon substitution at Cys816 of IRS2, (rs4773092), is associated with an auditory component of schizophrenia; this supports the notion, with the usual caveats regarding RNA stability, that IRS2 may also be translationally regulated, for example at its N-hCR." (PMID 26178806, 2015). "Of particular interest are the SLC6A12 gene coding for a GABA transporter previously associated with negative symptoms in schizophrenia and the insulin receptor substrate 2 which has been proposed to regulate dopamine cell morphology." (PMID 35105872, 2022).
squamous cell carcinoma (2 papers, 2019 to 2023). A carcinoma arising from squamous epithelial cells. "In this study, we assessed the expression patterns of IRS-1 and IRS-2 in NSCLC to identify associations between IRS-1 and IRS-2 expression levels and survival outcomes in the two major histological subtypes of NSCLC, adenocarcinoma (ADC) and squamous cell carcinoma (SCC)." (PMID 31393907, 2019). "High IRS-2 expression was significantly associated with decreased overall survival in adenocarcinoma (ADC) patients, whereas low IRS-1 cytoplasmic expression showed a trend toward association with decreased overall survival in squamous cell carcinoma (SCC) patients." (PMID 31393907, 2019).
Stroke (2 papers, 2025). Sudden impairment of blood flow to a part of the brain due to occlusion or rupture of an artery to the brain. "In this study, we found that all three biomarkers, ABCA1, CLEC4E, and IRS2, were associated with the activation of NET formation and infiltration levels of neutrophils in the IS, implying their importance in stroke." (PMID 40264650, 2025). "Nevertheless, the exact role of IRS2 in strokes remains unclear." (PMID 40264650, 2025).
triple-negative breast carcinoma (2 papers, 2023 to 2024). An invasive breast carcinoma which is negative for expression of estrogen receptor (ER), progesterone receptor (PR), and human epidermal growth factor receptor 2 (HER2). "In the first step, SUM-159 and MDA-MB-231 triple-negative breast carcinoma cells were electroporated with the most efficient gRNA complexed with Cas9 protein, and a donor fragment containing the DFN-cassette with left and right homology regions corresponding to the IRS2 genomic sequence." (PMID 39305958, 2024).
acute myeloid leukemia (1 paper, 2016). Acute myeloid leukemia (AML) is a group of neoplasms arising from precursor cells committed to the myeloid cell-line differentiation. "Erythropoeitin induces IRS2 upregulation in primary erythroblasts and in human acute myeloid leukemia cells UT7." (PMID 26755644, 2016).
Anxiety (1 paper, 2022). Intense feelings of nervousness, tension, or panic often arise in response to interpersonal stresses. "Elevations in the levels of IR, IRS2, and neurogenesis markers after insulin administration support a decrease in anxiety-like behaviors and an increase in learning and memory in rats." (PMID 36474571, 2022).